ENSG00000286007 (novel protein)
Gene: Protein-coding gene on chromosome 17 (7,428,861 to 7,436,278, forward strand). Ensembl gene ENSG00000286007.
Genetic constraint (gnomAD): Missense variants: 51 observed, 68.12 expected, observed/expected ratio (o/e) 0.75, 90% interval 0.6 to 0.94. Synonymous variants: 25 observed, 26.35 expected, observed/expected ratio (o/e) 0.95, 90% interval 0.69 to 1.33.